IGF1R (insulin like growth factor 1 receptor)
Diseases named in the same sentence as IGF1R in open-access papers (continued):
Sharing a sentence is not in itself a finding about the gene and the disease.
tumor (continued). "Recent studies have reported that overexpression of IGF1R and HMGA2 enhances tumor growth and migration in prostate cancer and colorectal cancer, respectively." (PMID 29507664, 2018). "In conclusion, our study identifies let-7c as a novel tumor suppressor of HNSCC that inhibits cell proliferation, migration, and EMT through repression of IGF1R and HMGA2 expression." (PMID 29507664, 2018). "In conclusion, the major finding of our study is that miR-497 and miR-99a synergistically target IGF1R and mTOR, thereby impeding the HCC tumor growth." (PMID 28624790, 2017). "We then assessed the correlation of these mRNA levels with tumor stage, activation of the INSR/IGF1R receptors (indicating activation of the IGF pathway) and the antiproliferative efficacy of an inhibitor of IGF1R tyrosine kinase." (PMID 28882129, 2017). "Previous studies have suggested that IGF1R signaling is involved in both acquired EGFR TKI resistance in NSCLC and induction of EMT in some types of tumor." (PMID 29190911, 2017). "Preclinical data have demonstrated that combined inhibition of IGF-1R and EGFR resulted in an enhanced anti-tumor effect in xenograft models." (PMID 28002810, 2017). "Here, we have demonstrated that the use of specific inhibitors to the pathways which we identified as induced in PIK3CA‐mutant tumors, such as STAT3, β‐catenin, and IGF‐1R, potentiates the cytotoxic effect of PI3K inhibitor on mutant PIK3CA tumor cells." (PMID 28296140, 2017). "We measured the protein expression level of IGF1R in 62paired HCC samples and adjacent non-tumor tissue samples by IHC." (PMID 29156819, 2017). "We so further quantified INSR/IGF1R phosphorylation, by RPPA on 97 tumors from the FBLAD-Exon tumor set." (PMID 28882129, 2017). "To further investigate the mechanisms of antitumor efficacy of fusion proteins in vivo, we analyzed the phosphorylation and total expression levels of EGFR, IGF-1R, AKT and ERK in xenograft tumor tissues by Western blot." (PMID 28460483, 2017). "To estimate the frequency of IGF1R amplification in Type IV, we analyzed the copy number in 46 FFPE samples using quantitative real‐time PCR for macrodissected tumor DNA which detected >fourfold amplification in one tumor sample (patient #17)." (PMID 27891760, 2017). "We found that MG tumor latency time in X10 and IGF1 (compounds with a high affinity towards the IGF1R) treatment groups was significantly decreased." (PMID 28173837, 2017). "These discouraging results could be explained by the emergence of tumor cell independence from their microenvironment due to intraclonal heterogeneity, the involvement of other growth factors and the existence of hybrid receptors composed of IGF-1R and 2R that can be activated by all IGF ligands." (PMID 29387053, 2017). "By binding to the type 1 IGF receptor (IGF1R), IGF-II promotes tumor growth through autocrine, paracrine and endocrine pathways." (PMID 27486969, 2017). "Testing of the RNA expression levels of the four upregulated genes in the tumour xenografts showed that decreased expression of the ADAM10 and IGF1R genes in the RPPH1 knockdown group." (PMID 29200969, 2017). "Currently, several anti-IGF1-R antibodies and TKI molecules have demonstrated that these targeting approaches can induce strong anti-tumor activities and are under clinical investigation." (PMID 29262576, 2017). "EGFR and the insulin-like growth factor-1 receptor (IGF-1R) play an essential role in cell proliferation and tumor progression." (PMID 28931402, 2017). "Chronic treatment with compounds that possess a high affinity towards the IGF1R, IGF1 and the insulin analogue X10, significantly decreased the tumor latency time." (PMID 28173837, 2017). "Tumor cells were shown to express IGF-1R, and binding of IGF-1R to its ligand promotes cell growth and survival through activation of PI3K/Akt and MAPK pathways." (PMID 28915700, 2017).
tumor (continued). "Immunohistochemistry studies of these 36 HCCs (tumor regions) exhibited strong positive GPC3 staining in 25 and positive IGF-1R staining in 18, and the expression of GPC3 and IGF-1R was correlated (p < 0.005 by Fisher's exact test)." (PMID 29113314, 2017). "Immunohistochemical (IHC) analysis was conducted on FFPE tumor to investigate IGF-1R and EGFR expression, using an IGF-1R IHC protocol recently optimized for sensitivity and specificity." (PMID 27200287, 2016). "Several tumour-promoting biomarkers such as EGFR, IGF1R, IR and c-Met are also co-overexpressed in TNBC." (PMID 27502396, 2016). "Like IGF-1R, all of these RTKs signal via AKT to enhance tumor cell growth and survival, and the level of AKT phosphorylation was found to correlate with poor survival." (PMID 27200287, 2016). "Evidences suggest a role of IGF-1R in the progression of tumor and a functional cross talk between EGFR and IGF-1R." (PMID 27895663, 2016). "In conclusion, in this study we show that both 3-hydroxyalkyl-4-ene-1-ynes isolated from sponge C. vasculum target IGF-1R, resulting in degradation of IGF-1R β in a tumor selective manner." (PMID 27384680, 2016). "They contribute a lot to tumor initiation and development by controlling the expression and function of tumor suppressor genes, including K-RAS, ELK1, MYO6, BCL2, ERK5 and IGF1R." (PMID 27626488, 2016). "In summary, we demonstrate that ABT-869 and chemotherapies act synergistically to inhibit the tumor growth and angiogenesis in vitro and in vivo through simultaneous blockade of EGFR-, IGF1R- and VEGR2-mediated AKT/mTOR signaling pathways." (PMID 27387652, 2016). "Because IGF1R represents a key molecule in the hypoxic tumor microenvironment, IGF1R inhibitors appear therapeutically promising in PDAC characterized by IGF1R overexpression." (PMID 27487118, 2016). "Possible explanations lie in tumour heterogeneity, issues related to assay sensitivity, and direct activity of metabolites of rociletinib like IGF-1R (insulin like growth factor-1 receptor)." (PMID 27433281, 2016). "As IGF1 and GAS6 are secreted by activated PSCs, we investigated the dependency of IGF1R and AXL activity on the PSC-induced tumor cell phosphoproteome." (PMID 27087446, 2016). "Consequently, miR-1275 could play a role in ES tumor progression by regulating IGF1R." (PMID 27144561, 2016). "In SK-N-MC tumor xenografts, ERBB4 and EGFR were the prominent RTKs detected by the phospho-proteome array together with INSR and IGF1R." (PMID 27374103, 2016). "Combined IGF1R and AXL inhibitors are required to block the PSC-induced tumor cell phosphoproteome—suggesting a Boolean “OR” axis between PSC IGF1/GAS6 and PDA pAKT." (PMID 27087446, 2016). "This study found that after silencing Klotho gene, p-IGF-1R / p-AKT levels and cell invasion were significantly increased, whereas tumor cell apoptosis was significantly decreased." (PMID 27779100, 2016). "In agreement, cell-specific analysis of PDA proliferation in homo and heterocellular cultures revealed increased tumor cell proliferation under heterocellular conditions (via SHH, IGF1R/AXL, and AKT activity)." (PMID 27087446, 2016). "Fluorescence immunostaining was performed on frozen tumor samples from HCT 116 tumors and confirmed the presence of IGF-1R on the cancer cell membranes." (PMID 26731105, 2016). "Simple pharmacological perturbation of reciprocal nodes (e.g., IGF1R, AXL, AKT, etc.)in existing PDA GEMMs will in principle affect all cell types (e.g., tumor cells, PSCs, immune cells) and cannot provide axis-specific information in vivo." (PMID 27087446, 2016).
tumor (continued). "By employing PLA we confirmed both a block in phosphorylation of IGF-1R in NSCLC cells but also degradation of IGF-1Rβ upon compound 1 treatment, the later also found in tumor cells of different origin." (PMID 27384680, 2016). "In recent studies, we attenuated IGF-1R signaling in the MMTV-Wnt1 tumor model and demonstrated decreased tumor latency, increased tumor incidence, and development of a metastatic tumor phenotype." (PMID 26106366, 2015). "Our results offer mechanistic insights into the interplay between tumours and their healthy counterparts within the TME in the development of adaptive–evasive abilities in the face of an IGF-1R blockade." (PMID 26465273, 2015). "Combining an anti-IGF1R antibody with MEDI-573 offers a better antitumor effect because of greater inhibition of IGF1 and IGF2 signaling in cancer cells and tumor angiogenesis is inhibited." (PMID 25699021, 2015). "Co-targeting ERBB2 and IGF1R reduces Erk/AKT activation, cell proliferation, in vitro invasion, and xenograft tumor growth to a greater extent than targeting either receptor individually." (PMID 25964777, 2015). "Down-regulation of FAK results in degradation of IGF1R, and dual inhibition of FAK and IGF1R produces synergistic anti-tumor effects." (PMID 25749031, 2015). "The SCLC group had strongly positive c-Kit in four tumors, EGFR in two, IGF1R in two, and KDR in three, for a total of 10 (16 %) SCLC tumors with a strongly positive RTK (one tumor was strongly positive for both c-Kit and IGF1R)." (PMID 25989941, 2015). "Although the mechanisms of IGF-1R in EMT are unclear, the downregulation of IGF-1R is sufficient to drive tumor cell migration, indicating that the presence of IGF-1R is critical for inducing an EMT-like phenotype." (PMID 25663868, 2015). "Combined inhibition of IGF1R/IR along with AKT inhibition and ER deprivation enhances the anti-tumor effect in vivo." (PMID 25964777, 2015). "This allows for not only targeting of IGF-1R but also the INSR isoform, insulin receptor A (INSR-A), which can mediate tumor growth." (PMID 26217584, 2015). "Anti-IGF-1R therapies suppressed tumor growth and development in mouse xenografts of human TNBC, providing rationale for targeting IGF-1R alone or in combination with agents targeted against other receptors in TNBC." (PMID 26350593, 2015). "The efficacy of IGF-1R TKIs alone or in combination with Src inhibitors was analyzed using MTT assays, colony formation assays, flow cytometric analysis, and xenograft tumor models." (PMID 26041671, 2015). "Because tumor spheroids mimic tumor migratory characteristics, we formed MDA-MB-231 and BT549 IGF1R-KD spheroids and compared these results to the EV control groups." (PMID 25749031, 2015). "Most IGF pathway members, including IGF1R itself, tend to be more highly expressed in luminal A and luminal B tumors and comparatively underexpressed in basal and ERBB2+ tumor types." (PMID 25964777, 2015). "QRT-PCR was performed to investigate the expression of IGF1R in LSCC tissues; the result shows that this gene was significantly higher in tumor tissues than the adjacent normal tissues." (PMID 25184138, 2014). "IGF1R mediates a variety of important molecular signaling pathways via its adaptor protein IRS and plays a key role in regulating tumor development." (PMID 25184138, 2014). "Further in vivo experiment also displayed the importance of IGF-1R in SKOV3-T, for the mean tumor volume of SKOV3-T was ~1257 mm3, while SKOV3 KD was ~1115 mm3." (PMID 25424625, 2014). "High ALDH activity, characteristic for tumor initiating cells, as well as ALDH1 mRNA levels remained unaltered upon IGF1R/INSR receptor overexpression." (PMID 24809298, 2014).
tumor (continued). "OSI-906 (Astellas Pharma Inc., Tokyo, Japan) is a potent, selective, orally bioavailable, dual IGF1R/INSR TKI, which has demonstrated in vivo efficacy in tumor models and is currently in clinical evaluation." (PMID 24904527, 2014). "Our data demonstrated that MK-0646 decreased tumor growth in CRC xenografts in vivo and is supported by downregulation of IGF-1R and pIGF-1Rβ in western blot analysis." (PMID 24173770, 2014). "Incubating tumour cells with gefitinib or erlotinib led to an increased heterodimerisation of IGF1R and EGFR resulting in a pronounced IGF1R-activation and therefore amplified activation of downstream mediators." (PMID 25444177, 2014). "The convergence of IGF1R-mediated cell survival pathways and BRCA1-mediated tumor protective pathways is of major basic and clinical relevance." (PMID 24904527, 2014). "We carried out in vitro and in vivo experiments to evaluate the effects of miR-194 and its possible direct targets, IGF1R and CDH2, in tumor growth and metastasis of SOSP-9607 and U2-OS cells." (PMID 25096247, 2014). "In both the primary tumor and the metastases, Claudin-4 was most frequently expressed, followed by GLUT-1, CAIX, EGFR and IGF1R." (PMID 25417118, 2014). "In line with the in vitro data overexpression of IGF1R and INSRA but not INSRB significantly increased tumor area, while downregulation of the IGF1R and the INSR strongly reduced tumor growth in the CAM-assay." (PMID 24809298, 2014). "Indeed, the marked down-regulation of miR-378a-3p, miR-1 and miR-133a, and the concomitant up-regulation of IGF1R observed in RMS tumours could explain why cancer cells are prohibited from undergoing terminal differentiation despite their commitment to a myogenic pathway." (PMID 25427715, 2014). "Overall, results indicate that miR-99a functions as a tumor metastasis suppressor in OSCC cells and mutually regulates IGF1R expression in a reciprocal regulation." (PMID 24410957, 2014). "Conversely, IGF1R mRNA was found to be up-regulated in tumour tissue and stimulated CRC monocytes from early stages revealing a role of IGF1R in tumour initiation." (PMID 25403427, 2014). "IGF-1R is overexpressed in EOC and, acting in an autocrine way, can influence tumor cell growth, proliferation and apoptosis." (PMID 24103397, 2013). "Overexpression of miR-140 inhibits tumor growth and metastasis of NSCLC through directly targeting IGF1R." (PMID 24039995, 2013). "To explicate mechanisms of tumor resistance, we compared patient #2 with two EWS patients (patients 3&4) who initially responded to IGF1R+mTOR inhibitor therapy." (PMID 23922674, 2013). "In a phase I dose-expansion trial combining the IGF-1R inhibitor cixutumumab and mTOR inhibitor temsirolimus, 7 of 20 patients had either stable disease or responses by RECIST criteria (35%), and 29% had tumor regression." (PMID 23383402, 2013). "Other approaches are tumor vaccines against HER2, a dual HER2 and insulin-like growth factor-1 receptor (IGF-1R) blockade, and inhibition of heat-shock protein 90 (HSP90)." (PMID 24027583, 2013). "Low grade indicates that the distribution of IGF-1R staining is less than 50% of tumor area, whereas high grade indicates that the distribution of IGF-1R staining is more than 50% of tumor area." (PMID 24103397, 2013). "Our data showed that tumor cell viability was significantly reduced and tumor cell apoptosis enhanced by irradiation following inhibition of both EGFR and IGF1R, as compared to irradiation treatment alone or irradiation plus blocking of either receptor." (PMID 23950876, 2013). "However, our in vivo data for tumor growth after treatment with HI and X10 are consistent with the in vitro signalling and proliferation data, which show X10 is only a slightly more potent stimulator of proliferation and signalling downstream of IR/IGF-1R than HI in MC38 cells." (PMID 24260289, 2013). "Expression rates increased with tumor grade for GLUT1, CAIX, and CXCR4 (all p < 0.001), but decreased for IGF1R (p < 0.001)." (PMID 24206539, 2013).
tumor (continued). "Our data show that co-targeting EGFR and IGF-1R plus irradiation significantly reduced S phase and arrest cells at G0/G1 phase in MDA-MB-468 cells, profound tumor cell kill was observed, therefore, the cells were sensitized to irradiation." (PMID 23777562, 2013). "In atypical teratoid/rhabdoid tumor cells of the central nervous system, NVP-AEW541 was shown to inhibit cell proliferation and survival by blocking IGF-1R and IR activation by autocrine loops involving IGFs and insulin." (PMID 23525758, 2013). "The tumor endometrium expressed significantly lower levels of IGF-1, IGF-1R, and IGF-2, and significantly higher levels of IGF-2R and IGFBP-3, compared with tumor-adjacent endometrium (p < 0.05)." (PMID 22720981, 2012). "Thus, specific inhibition of STAT5b/IGF-1R could be another strategy for blocking tumor growth." (PMID 22792362, 2012). "We further study the correlation of IGF-1, IGF-1R, IGF-2, IGF-2R, and IGFBP-3 mRNA expression with ERα and ERβ mRNA expression in tumor, tumor-adjacent and control endometria." (PMID 22720981, 2012). "The mRNA level of IGF-1, IGF-1R, IGF-2, IGF-2R, and IGFBP-3 was significantly higher in tumor and tumor-adjacent endometrium than that in control endometrium (p < 0.05)." (PMID 22720981, 2012). "Recombinant human IGFBP-3 showed significant inhibition of tumor growth in trastuzumab resistant HER2 and IGF-1R overexpressing cell lines and in vivo synergistic interaction with antiHER2 therapy by decreasing bioavailability of IGF-1 ligand." (PMID 22415797, 2012). "We tested the expression of IGF-1, IGF-1R, IGF-2, IGF-2R, IGFBP-3, ERα and ERβ mRNA on 58 tumor tissue samples and 31 tumor-adjacent endometrial tissue samples from patients with EAC and 42 normal endometrial tissue samples, using RT-PCR." (PMID 22720981, 2012). "Among these, enhanced effects on apoptosis enhancement, cell cycle arrest, and reduced tumor load in the 5TMM model in vivo were achieved by combining a novel HDAC inhibitor, LBH589 (panobinostat), with the IGF-1R inhibitor PPP." (PMID 22348393, 2012). "Accordingly, in vitro experiments showed combined inhibition of IGF1R and EGFR activity to reduce tumor cell proliferation synergistically." (PMID 22815959, 2012). "A panel of tumor-specific markers (GLUT1, EGFR, HER2, IGF1-R, MET, and CAIX) was in the present study able to 'detect' 45.5% of all cancers and 55.6% of ductal cancers." (PMID 22695343, 2012). "We then detected the protein expression of IGF-1R, IGF-2R, ERα and ERβ on 80 tumor samples from patients with EAC, 33 samples from patients with atypical hyperplasia, 22 samples from control patients, using immunohistochemistry." (PMID 22720981, 2012). "Including TfR, Mammaglobin, and MUC1 to the panel of highly tumor-specific markers GLUT1, MET, EGFR, IGF1-R, CAIX, and HER2 increased the detection rate from 45.5% to 49.8% (TfR), 56.4% (Mammaglobin), and 98.1% (MUC1), respectively." (PMID 22695343, 2012). "In conclusion, we have demonstrated a novel mechanism by which Lin28b over-expression promotes tumour progression via additional Let-7 gene targets such as CCND2, IGF2BP2, and IGF1R." (PMID 23482325, 2012). "The most widely expressed tumor-specific protein in our cohort was GLUT1, positive in 20.3% of the cancers, followed by EGFR (17.4%), IGF-1R (12.8%), HER2 (10.4%), CAIX (9.5%), and MET (8.9%)." (PMID 22695343, 2012). "Immunohistochemical detectability of EGFR, IGF-1R, and phospho-HER2 in our study was the best for tissue fixed with standard formalin throughout all xenograft tumor models." (PMID 22814649, 2012).